EGFR (epidermal growth factor receptor)
Diseases named in the same sentence as EGFR in open-access papers (continued):
Sharing a sentence is not in itself a finding about the gene and the disease.
cancer (continued). "Furthermore, the EGFR signal can crosstalk with β-catenin to promote frequencies of invasiveness and metastasis of cancer cells." (PMID 33827580, 2021). "Therefore, a therapeutic strategy directed at inhibiting EGFR-mediated signaling pathways is a feasible therapeutic option in cancer patients." (PMID 34804932, 2021). "In adults, the dysregulation of EGFR is involved in many pathological mechanisms of human diseases, such as renal fibrosis, coronary artery disease, autoimmune disease, chronic obstructive pulmonary disease, and cancers." (PMID 33562150, 2021). "Thus, the EGF/EGFR signaling pathway is recognized as an important molecular target in cancer therapy." (PMID 32901097, 2021). "Thus, targeting autophagy can be one of the approaches to overcome resistance to anti-cancer drugs as well as anti-EGFR therapy." (PMID 34829834, 2021). "We selected a potential radio- and chemo-therapeutic drug specific for EGFR-overexpressing cancers." (PMID 33672989, 2021). "Here, we describe a novel mode of cooperation of EGFR and FAK signalling, which converge on ezrin, and has provided the opportunity to investigate possible treatments such as targeting FAK and/or ezrin in combination with EGFR to overcome EGFR TKI resistance in cancer cells." (PMID 34375550, 2021). "Some roles described for the physiological functions of the cell are exploited by cancer cells to their advantage to allow the self-renewal of the cancer stem cells, to increase translation of oncogenes such as EGFR, MYC, TAZ, MAPKAPK2 and to use shelter systems to allow cell survival." (PMID 34530916, 2021). "Recent studies implied that inhibiting EGFR pathway in cancer cells modulated cytokine secretion." (PMID 34393797, 2021). "However, unsatisfying treatment effects, terrible side-effects, and development of drug resistance are current insurmountable challenges of EGFR targeting treatments for cancers." (PMID 34322025, 2021). "EGFR is a type of membrane tyrosine kinase receptor that is overexpressed in 30–60% of GCs, and it initiates an intracellular signal pathway that promotes cancer cell proliferation, cell migration, and angiogenesis." (PMID 35069035, 2021). "Additionally, they established that P2RY12 activation on cancer cells induces cell proliferation through EGFR signaling." (PMID 34589424, 2021). "On the one hand, anti-cancer compounds containing a BPA conjugate with an epidermal growth factor (EGF) ligand or anti-EGFR antibody (mAbs, cetuximab (C225)) or anti-EGFRvIII mutation antibody (L8A4), and specifically recognize wild-type EGFR and EGFRvIII." (PMID 34094980, 2021). "Epidermal growth factor receptor I (EGFR) is overexpressed in many cancers." (PMID 33535661, 2021). "However, accumulated evidence indicates that HER3 plays a crucial role in cancer cell survival and drug resistance, especially in EGFR- or HER2-targeting therapy in certain malignancies." (PMID 33801379, 2021). "Overall, erlotinib inhibited PD-L1 expression—another manner in which EGFR inhibitors may augment T-cell-mediated cancer killing." (PMID 34680249, 2021). "Moreover, suppression of facilitative glucose transporter Glut was found to mediate the anti-cancer activity of TKIs in NSCLC cell lines bearing wild-type (wt) or mutant EGFR." (PMID 34155348, 2021). "In some cases, an increase in the amount of EGFR in cancer was observed after radiotherapy." (PMID 34094980, 2021). "The EGFR plays key roles not only in normal cellular functions but also in the development of several types of cancer cells, and therefore, it is the therapeutic targets of several anti-cancer drugs." (PMID 34799560, 2021). "Likewise, increased pSTAT3 and EGFR in resistant TNBC cells would favor growth factor stimulated cancer growth." (PMID 34944900, 2021). "The EGFR pathway is critical for the growth and invasive activities of cancer cells." (PMID 34174844, 2021).
cancer (continued). "Furthermore, DOX-loaded EGFR-MIP NPs decreased the cell viability of EGFR-overexpressing MDA-MB-468 cancer cells (lower than 75%) in comparison to free DOX (more than 90%) and control NPs (~100%)." (PMID 34208380, 2021). "Consistent with our results, suppression of EGFR by AMPK was observed in cultured cancer cells." (PMID 34748042, 2021). "Nevertheless, galectin-3 has a regulatory role in cancer stemness related pathways beside other pathways the EGFR/FGFR pathway is also involved and it was published that OPN induced migration and invasion is strongly associated with activation of different EGF receptors." (PMID 34257527, 2021). "Therefore, disruptions to EGFR-dependent pathways often lead to the development of skin fragility diseases or epithelial cancers and therefore EGFR has been a popular target for cancer." (PMID 34375550, 2021). "Notch1 and EGFR are two surface receptors activating different cellular processes in cancer cells." (PMID 33922104, 2021). "Our findings suggest that EGFR-YAP/TAZ signaling plays a growth-promoting role in cancers harboring EGFR alterations, and that inhibition of YAP/TAZ in combination with EGFR might be beneficial to prevent treatment resistance and cancer recurrence." (PMID 34725466, 2021). "Under this scenario, we hypothesized that the transfer of EV miRNAs between EGFR-mutant and wild-type cancer cells mediates the response of EGFR-TKI in heterogeneous EGFR-mutant NSCLC." (PMID 33671000, 2021). "Others have shown that DNM2 downregulation promotes EGFR signalling and cancer cell motility." (PMID 34831480, 2021). "Further, EGFR-targeting therapies suppress YAP/TAZ, and loss of LATS1/2-mediated YAP/TAZ activation confers therapy resistance, thus offering insights into potential drug resistance mechanisms in cancers with activated EGFR." (PMID 34725466, 2021). "EGFR inhibitors such as gefitinib and erlotinib have been developed to treat cancer." (PMID 34419139, 2021). "In particular, with regard to the common tyrosine-kinase inhibitors (TKIs), such as gefitinib, erlotinib, or afatinib, their role in cancer has been already shown, especially in NSCLC patients, which show mutations activating the epidermal growth factor receptor (EGFR)." (PMID 34830058, 2021). "As previously observed in a variety of cancer models, a functional signature of this EGFR-TKI persisters (i.e., erlotinib) is the capacity to revert back to sensitivity after an extended drug holiday (previous experimental observations vary from 20 to 40 passages)." (PMID 33850249, 2021). "We conclude by listing all clinically approved anti-cancer drugs targeting either EGFR or HER2." (PMID 34206026, 2021). "Inhibition of EGFR-downstream pathways is able to interfere with cancer growth." (PMID 34440249, 2021). "EGFR is a therapeutic target for multiple types of cancer including NPC." (PMID 34178975, 2021). "On the basis of literature findings on the transactivation of EGFR by IL-1β and the involvement of EGFR in TF expression in other cancer cell types, a Western blot analysis of EGFR phosphorylation at Tyr1068 and Tyr845 in IL-1β-stimulated A549 cells was performed." (PMID 34205482, 2021). "Our data suggests that Albu-LiTE-HB can discriminate between cells with different levels of antigen expression, potentially providing a strategy for targeting antigens that are highly expressed by cancer cells but have lower expression in normal tissues, such as EGFR." (PMID 33686177, 2021). "EGFR is one of the most successful pharmacological targets of anti-cancer drugs." (PMID 34206026, 2021). "Understanding the mechanisms of PIKfyve inhibitors may improve cancer treatment particularly for EGFR overactivated NSCLC." (PMID 33597819, 2021). "Besides, they preserved the information of both movement speed and pattern of EGFR, which, we believe, hold the key in distinguishing subtypes of cancer cells." (PMID 34390568, 2021).
cancer (continued). "Kinase inhibitors have shown great potential as a TNBC regimen due to their activity as antitumor and antiangiogenic therapies by targeting genes and pathways that play a role in cancer development and proliferation, like targeting EGFR, RON, MET, mTOR, BRAF, MEK, Src, and Bcr/Abl." (PMID 34944904, 2021). "Additionally, systemic treatments including chemotherapy and targeted therapies, usually anti-VEGF or anti-EGFR antibodies, are used throughout the entire cancer continuum of care and are the subject of many currently running trials." (PMID 32974773, 2021). "Most human DHHC-PATs are localized to endomembrane compartments such as Golgi, endosomes, endoplasmic reticulum, with only two proteins, DHHC20 and DHHC21, found at that the PM, which mediate epidermal growth factor receptor (EGFR) signaling in cancer and inflammatory responses." (PMID 33980819, 2021). "Treatment with navitoclax (or ABT-263, a BH3 mimetic that inhibits the anti-apoptotic factors BCL-xL and BCL-2) to enhance “free” cellular BIM levels or derepression of BIM expression by depletion of ZEB1 both led to resensitization of mesenchymal EGFR-mutant cancers to targeted therapy." (PMID 34071428, 2021). "The results described here indicate that such a technology could be applied as a generic CDC-enhancing tool for existing direct targeting mAb with a range of cell surface targets, such as CD20 or EGFR to augment their efficacy and improve anti-cancer therapy." (PMID 34475514, 2021). "GCs may be used to treat side effects of cancer therapies, raising the question that if prednisone or other GCs are used to treat side effects of EGFR TKIs, a beneficial effect of combining EGFR inhibition plus prednisone would have quickly become apparent." (PMID 34853306, 2021). "Furthermore, EGFR-TKI treatment increased IL-6 secretion in cancer cells, suggesting aggravation of lung injury." (PMID 33466795, 2021). "In addition, EGFR houses a single polypeptide backbone chain that is understood to be an important component in exploring effective treatments and screening of cancers, such as CRC." (PMID 33498632, 2021). "Indeed, we found that osimertinib and other EGFR-TKIs selectively downregulated the levels of DR4 including cell surface DR4 in EGFRm cancer cell lines in vitro and in vivo." (PMID 33664875, 2021). "For example, altering the expression of different EGFR isoforms or subtypes may impede the anti-cancer effects of the EGFR inhibitors." (PMID 34681918, 2021). "Moreover, the inhibition of EGFR signaling by gefitinib has been shown to alter the immune environment of the targeted cancer in vitro and in vivo, probably by reducing the number of Tregs in the tumors." (PMID 34113560, 2021). "EGFR-targeting therapies have dramatically altered the treatment landscape of a number of cancers." (PMID 34069119, 2021). "Furthermore, it also impedes cancer cells’ survival and suppresses their metastatic ability through the downregulation of EGFR pathways and inhibition of MMP activities." (PMID 34299604, 2021). "Similarly, a Neuro2A (N2A) cell line expressing membrane‐anchored‐α‐EGFR nanobody also produces EVs with a high affinity for EGFR on cancer cells." (PMID 33643546, 2021). "Anti‐EGFR or BRAF targeted therapies were not recommended in either pancreatic head or body/tail cancers because of the extremely low druggable mutation frequencies." (PMID 33452856, 2021). "In vitro, EGFR EVs were shown to be involved in several cancer hallmarks like inducing angiogenesis, sustaining proliferating signaling, evading growth suppression and immune destruction, promoting inflammation, resisting cell death, and activating invasion and metastasis." (PMID 33995103, 2021).
cancer (continued). "Therefore, it is widely assumed that cancer cells become “addicted” to uncontrolled EGFR-mediated growth and survival signals." (PMID 35052732, 2021). "For instance, AuNPs were conjugated with cetuximab antibody by Li and coworkers to enhance the specificity of AuNPs to human cancer cells through the conjugation to tumor-specific ligands such as EGFR, which is expected to be a promising candidate for cancer therapy." (PMID 34437513, 2021). "213Bi-anti-EGFR-MAb selectively eradicates cancer cells that show EGFR overexpression." (PMID 33737524, 2021). "In the incomplete PDT treatment groups (LCP siEGFR+LCP Pyro PA without light and LCP siEGFR+PBS+light), the anti-tumorigenic effects of the LCP siEGFR NPs were observed as LCP siEGFR was effectively delivered to cancer cells resulting in lower levels of EGFR mRNA and protein expression." (PMID 34575510, 2021). "It is known that the main output of over-activated EGFR/Ras signaling is the induction of a complex and dynamic set of transcriptional networks, leading to changes in the gene expression signature and metabolic state of cancer cells." (PMID 34411095, 2021). "Epidermal growth factor receptor (EGFR) activates PLCγ1 and helps in cancer cell mitogenesis." (PMID 34793541, 2021). "We speculate that combined inhibitors for both SOCE and EGFR pathways could achieve better anti-cancer effects than single agent alone for GE cancer." (PMID 34012400, 2021). "Furthermore, MSA treatment inhibited EGFR pathway and subsequntly reduced Interleukin-6 (IL-6) secretion in the supernatant of cancer cell lines." (PMID 34393797, 2021). "However, there is a need to conduct further studies on the safety and efficacy of MET TKI in patients who have failed EGFR TKI therapy and in whom one of the main causes of resistance is the selection of a cancer cell clone with MET gene abnormalities." (PMID 34945842, 2021). "Alongside, EGFR enhances cancer cell invasiveness by harnessing the pro-invasive functions of TGFb." (PMID 34206026, 2021). "The structure of small peptides for targeting EGFR-active cancers may also be predicted by computer-assisted design (CAD)." (PMID 33981532, 2021). "Interestingly, we found a significant difference only at lower doses of PTX, suggesting that ET‐RBCEVs can enhance the efficacy of low dose PTX on EGFR‐positive cancer cells." (PMID 33643546, 2021). "A total of 159 patients, with 88 patients from Hunan Cancer Hospital and 71 patients from Xiangya Hospital with EGFR-mutant locally advanced/advanced NSCLC who were treated with A+T were matched to 159 patients who were treated with single-agent T using propensity score matching with 1:1 ratio." (PMID 34663309, 2021). "Hence, we assessed the expression profile of genes involved in these signaling pathways to clarify the contribution of EGFR inhibition into the mechanism of the anti-cancer activity of the compounds tested in CAL-27 and SCC-25 cells." (PMID 34201116, 2021). "EGFR‐mutant NSCLC was analyzed using the MSK‐IMPACT assay, a clinical test that detects mutations, copy‐number alterations, and select fusions involving 341 (version 1), 410 (version 2), or 468 (version 3) cancer‐associated genes." (PMID 33969622, 2021). "Thus far, oncogenic EGFR mutants portray an intriguing therapeutic target for anti-cancer treatment." (PMID 34070173, 2021). "Furthermore, a recent study showed that Akt is a novel binding partner of MIG6 to modulate its activation in several types of cancer cells expressing a low level of EGFR." (PMID 33693003, 2021). "Exaggerated activity of epidermal growth factor receptor (EGFR) drives various cancers." (PMID 34680266, 2021).
cancer (continued). "Hypoxia-induced secreted exosomes released from cancer cells contain plasma membrane receptors, including glucose transporter, EGFR, P-glycoprotein, and multidrug resistance protein 1; angiogenic proteins, such as VEGF, FGF, and angiogenin; and various noncoding RNAs, including miRNAs and lncRNAs." (PMID 33946823, 2021). "Pharmacological inhibition of EGFR/HER2 was shown to activate AMPK in cancer cells, indirectly suggesting that EGFR and AMPK may exert functionally opposing effects on the Tyr10 phosphorylation." (PMID 34748042, 2021). "It is known that 1,25(OH)2D3 inhibits the EGFR signaling pathway in cancer cells, and perhaps, PRI-2191 could contribute to a decrease in IL-8 levels by inhibiting this pathway in HCC827 cells." (PMID 33652978, 2021). "Targeting the EGFR with small-molecule inhibitors is a confirmed valid strategy in cancer therapy." (PMID 34771085, 2021). "Cinobufagin and cinobufotalin, having same acetylation and different hydroxy, exhibit better selectivity and higher efficiency against cancer cells with EGFR expression and PTEN deletion than resibufogenin, implying the acetyl group increases the inhibitory effect and 1-hydroxy is not critical." (PMID 34925034, 2021). "Further exploration of the role of inflammatory cytokines in EGFR-TKI resistance could possibly unravel some of the mechanisms by which EGFR-TKI resistance occurs in cancer cells." (PMID 33466795, 2021). "For instance, ERK1/2 has been reported to play a role in driving EGFR internalization in cancer cells through the regulation of CCP formation, while components of the MAPK signaling pathways were found to have functional interaction with the trafficking machinery." (PMID 34344896, 2021). "EGFR has an important role in enhanced migration of cancer cell." (PMID 33639651, 2021). "Such situations may arise during the development of HPV(+) cancers that have mutations in PIK3CA (or downstream effectors) and/or become refractory to EGFR or PI3K inhibitors, which we and others reported can lead to MEK/ERK stimulation via other RTKs." (PMID 33481911, 2021). "Because each of these cancers retains expression and activation of the oncogenic EGFR allele, loss of EGFR codependence in these models was not intuitive." (PMID 34516823, 2021). "Importantly, the ASO sequences of triped 1 were designed to be effective silencers towards EGFR as well as towards EGFR variant III, playing a key role in cancer resistance to chemotherapy and radiotherapy." (PMID 34064412, 2021). "Interestingly, in study #8, cytoplasmic cyclin E was the only independent biomarker of BCSS alongside a large panel of other biomarkers including EGFR There is a growing body of evidence to support its oncogenic role in various cancer types." (PMID 34165702, 2021). "Interestingly, all significant results targeted known cancer driver genes such as EGFR, HER2, PIK3CA, and BRAF." (PMID 33872312, 2021). "Furthermore, studies have shown that cross-talk between the STAT3 and EGFR pathways attenuates the effects of standard therapies and EGFR-targeting treatments on cancer." (PMID 34063134, 2021). "Further, the combination of EGFR inhibitor (erlotinib) and GAbsiAXL synergistically enhanced apoptosis and inhibited cancer cell migration, demonstrating that RNA-based inhibition of AXL in the combination of chemotherapies may be beneficial in NSCLC." (PMID 33740988, 2021). "It is well known that the EGFR system plays a key role in cancer development." (PMID 34126069, 2021). "In our study, MAPK signaling, Ras signaling, ErbB signaling, and EGFR tyrosine kinase inhibitor resistance pathways were enriched in high immune-risk patients, specifying the highly proliferative status of cancer cells in high immune-risk patients." (PMID 33790969, 2021).